AQP3 (aquaporin 3 (Gill blood group))
Diseases named in the same sentence as AQP3 in open-access papers (continued):
Sharing a sentence is not in itself a finding about the gene and the disease.
melanoma (14 papers, 2010 to 2025). A malignant, usually aggressive tumor composed of atypical, neoplastic melanocytes. "To further investigate whether AQP3 inhibition by POTs underlies signal transduction mechanisms that affect melanoma progression, we evaluated the rate of melanoma cell migration before and after treatment with POTs." (PMID 32252345, 2020). "Recently, the organogold complex ST004 was identified as an AQP3 inhibitor, with its liposomal formulation demonstrating anticancer activity against melanomas in both in vitro and in vivo models." (PMID 39941100, 2025). "The inhibition of AQP3 peroxiporin activity in melanoma cell lines was recently reported, impairing cancer cell migration, proliferation and adhesion and highlighting the impact of AQP3 on melanoma progression." (PMID 39941100, 2025). "In MNT-1 and A375 melanoma cells, AQP3 blockage by gold compounds or transient silencing led to decreased intracellular ROS accumulation, suppressing cell adhesion, migration, and proliferation." (PMID 39125952, 2024). "In general, several studies by our groups have demonstrated that gold-based complexes are potent and selective inhibitors of aquaporin-3 (AQP3), a membrane transporter of water and glycerol that is overexpressed in melanoma." (PMID 39771545, 2024). "The ability of gold-based complexes to modulate AQP3 activity has made them promising molecules against cancer and particularly for melanoma management." (PMID 39771545, 2024). "Subsequently, we investigated if the POTs under study, in addition to the AQP3-inhibitory effect, would affect melanoma cell migration." (PMID 32252345, 2020). "This prompted us to investigate the possible effect of three Wells–Dawson and one Preyssler type polyoxotungstates (POTs) on AQP3 activity and evaluate their potential as anticancer drugs for melanoma therapeutics." (PMID 32252345, 2020). "Nevertheless, an earlier study documented the aberrant expression of AQP3 in melanoma cells, indicating that a new therapeutic treatment would result in its inhibition." (PMID 32351935, 2020). "Herein, we report for the first time the ability of polyoxotungstates (POTs), such as of Wells–Dawson P2W18, P2W12, and P2W15, and Preyssler P5W30 structures, to affect aquaporin-3 (AQP3) activity and impair melanoma cell migration." (PMID 32252345, 2020). "Although more investigations are needed to establish structure–activity relationships, it can nevertheless be assumed that it is the intact phosphotungstate that is responsible for the observed inhibitory effect on AQP3 activity and melanoma cell migration." (PMID 32252345, 2020). "In the present study, we firstly confirmed the highest expression level of AQP3 in a human melanoma cell line, in agreement with the human tumor phenotype." (PMID 32252345, 2020). "Summing up, we demonstrate that POTs affect the activity of AQP3 and impair the migration rate of melanoma cells, with P2W18 being the most potent." (PMID 32252345, 2020). "In particular, the aquaglyceroporin AQP3 was found aberrantly expressed in various human cancers including human skin cell carcinomas and melanoma." (PMID 32252345, 2020). "Although AQP3 overexpression has been demonstrated to contribute to chemoresistance in melanoma to arsenite, little is known about its role in chemosensitivity of GC to cytotoxic agents." (PMID 27867537, 2016). "Moreover, this new class of organogold compounds has demonstrated strong inhibition of AQP3 peroxiporin activity in melanoma cell lines, leading to an impairment in melanoma cell adhesion, cell proliferation and cell migration." (PMID 39941100, 2025). "Considering that AQP3 is overexpressed in melanoma, inhibiting AQP3 function may explain, at least in part, the potential of ST004 as an anticancer drug for melanoma." (PMID 39771545, 2024). "The anticancer properties of these compounds may be in part due to the blockage of AQP3-mediated permeability, unveiling their potential as anticancer drugs against melanoma tumors." (PMID 32252345, 2020).
melanoma (continued). "Thus, in addition to the effects on AQP3 activity, we further analyzed the effects of POTs in melanoma cell migration." (PMID 32252345, 2020). "Copper–phenanthroline compounds were shown to promote oxidative DNA damage, and Cu2+ compounds, including dichloro(1,10-phenanthroline) copper (II), Cuphen have also been reported as inhibitors of aquaporin-3 (AQP3), an aquaglyceroporin that is overexpressed in several carcinomas including melanoma." (PMID 32268611, 2020). "Furthermore, in human melanoma cells that showed high levels of AQP3 gene expression, we evaluated POT anticancer properties through their effect on cell viability and suppression of cell migration." (PMID 32252345, 2020). "In addition, metal-based compounds have been shown to specifically inhibit AQP3, a transmembrane protein overexpressed in melanoma cells." (PMID 31614947, 2019). "Moreover, a recent study reported an aberrant AQP3 expression in melanoma and proved that it significantly increases chemoresistance to arsenite treatment." (PMID 22624030, 2012). "The effect of P2W12 and P2W18 on melanoma cells that highly express AQP3 revealed an impairment of cell migration between 55% and 65% after 24 h, indicating that the anticancer properties of these compounds may in part be due to the blockage of AQP3-mediated permeability." (PMID 32252345, 2020). "Finally, the ability of polyoxotungstates (POTs), in particular P2W18, to inhibit AQP3 and impair melanoma cell migration was reported, suggesting that the well-known anticancer properties of these compounds may in part be due to the blockage of AQP3-mediated permeability." (PMID 35187089, 2022). "The expression of AQP3, as well as AQP1, AQP5, and AQP9 seem to be correlated with melanoma progression, indicating a common pattern of downregulation from the higher values in normal skin and benign nevi." (PMID 20805891, 2010). "Three proteins of this family (AQP1, AQP3, and AQP9) have probes that seem correlated with melanoma progression, all losing their expression in the process of going from normal skin to metastatic melanoma." (PMID 20805891, 2010). "It is not surprising that malignant melanoma shows no expression of AQP3 as normal melanocytes within the epidermis do not show AQP3 expression as demonstrated by our prior study." (PMID 34745849, 2021). "All 32 basal cell carcinomas, 9 sebaceous carcinomas, and 28 malignant melanomas were negative for AQP3 staining." (PMID 34745849, 2021). "Only focal AQP3 staining was seen in nevocellular nevus and no AQP3 staining in melanoma." (PMID 34745849, 2021). "No AQP3 staining was seen in basal cell carcinomas, sebaceous carcinomas, and malignant melanomas." (PMID 34745849, 2021). "AQP3 mRNA was detected in normal epidermis, seborrheic keratosis, solar keratosis, Bowen's disease, squamous cell carcinoma, eccrine poroma, apocrine carcinoma, and sebaceoma; however, AQP3 mRNA was absent in basal cell carcinoma, nevocellular nevus, or malignant melanoma." (PMID 34745849, 2021).
pancreatic cancer (14 papers, 2012 to 2026). "The strong association found between AQP5 and EGFR, and the associations between AQP3/AQP9 and c-Jun in pancreatic tumor tissues highlight the implications of AQPs in the settings of tumorigenesis." (PMID 40305202, 2025). "In pancreatic cancer cells, AQP3 was found to promote tumor proliferation through the activation of the mammalian target of rapamycin (mTOR) signaling pathway." (PMID 39941100, 2025). "Recently, we reported the modulation of the most cancer-associated AQPs—AQP1, AQP3, AQP5, and AQP9—in paired pancreatic tumors and adjacent healthy tissues from a pancreatic cancer cohort." (PMID 40305202, 2025). "In pancreatic cancer, inhibition of AQP3 by the inhibitor CuSO4 attenuated tumor cell migration, which suggested it was a potential therapeutic treatment agent for pancreatic cancer." (PMID 28264681, 2017). "Here, we silence peroxiporin aquaporin-3 (AQP3) on the pancreatic cancer cell line MIA PaCa-2 and compare clonogenic survival response to the wild-type." (PMID 28107421, 2017). "As a side note, some drugs, such as gemcitabine used for pancreatic cancer, are known to elevate peroxiporin, specifically AQP3, expression in cancer cells." (PMID 28107421, 2017). "Recently, we assessed the expression of tumor-associated AQPs (AQP1, AQP3, AQP5, and AQP9) in the same pancreatic cancer cohort, revealing AQP1 downregulation in tumor tissues, and AQP3 upregulation in low-invasiveness grade tumors compared to high invasiveness grade pancreatic tumors." (PMID 40305202, 2025). "AQP3 also facilitates the transport of glycerol, supporting metabolic flexibility and energy production in cancer cells under hypoxic or nutrient-deprived conditions, common in pancreatic tumors." (PMID 40305202, 2025). "Furthermore, our group reported that both AQP3 and AQP5 play a critical role in cancer cell migration in pancreatic cancer where cells silenced for AQP3 and AQP5 and those double-silenced (AQP3/AQP5) exhibited a significant impairment in cell migration." (PMID 39941100, 2025). "AQP3 can promote tumor growth of pancreatic cancer cells by activating the Mtor signaling pathway." (PMID 39346734, 2024). "Additionally, and more importantly, the silencing of peroxiporin AQP3 on pancreatic cancer cells suggests that accumulation of lethal intracellular H2O2 concentrations is prevented; consequently, allowing for an increase in clonogenic response." (PMID 28107421, 2017). "Previously, we have characterized the implication of AQP3 and AQP5 in ROS accumulation, cell adhesion, proliferation, and motility in human pancreatic cancer BxPC3 cells, further supporting their involvement in pancreatic cancer progression." (PMID 40305202, 2025). "To further validate the correlations found, we analyzed publicly available datasets using TNMplot and observed significant correlations between AQP3 and c-Jun (p < 0.01), and AQP5 with EGFR (p = 0.040) and CDH1 (p < 0.01) in pancreatic cancer." (PMID 40305202, 2025). "In vitro experiments using a human pancreatic cancer cell line confirmed that the transcriptional regulation of EMT and MAPK/ERK signaling pathways is influenced by AQP3 and AQP5 expression levels." (PMID 40305202, 2025). "In a previous publication, we investigated the prognostic value of AQP transcripts in the same pancreatic cancer cohort and discussed the correlations found among various AQP isoforms (AQP1, AQP3, AQP5, and AQP9)." (PMID 40305202, 2025). "For that, we cultured a pancreatic cancer cell line, BxPC3, that was screened for AQP expression, revealing high levels of AQP3 and AQP5 expression and much lower levels of AQP1 and AQP8." (PMID 40305202, 2025). "Altogether, our results highlight the potential role of AQP3 and AQP5 as prognostic biomarkers in pancreatic cancer." (PMID 40305202, 2025).
pancreatic cancer (continued). "In particular, AQP1, AQP3, and AQP5 enhance the motility and invasiveness of pancreatic cancer by facilitating actin cytoskeleton remodeling, enabling cancer cells to migrate efficiently through tissue barriers." (PMID 40305202, 2025). "In pancreatic tumor tissues, AQP5 was correlated with EGFR, and AQP3 and AQP9 were correlated with c-Jun." (PMID 40305202, 2025). "The observed correlations further support the role of AQP3 and AQP5 in pancreatic cancer progression and reinforce the clinical relevance of targeting AQPs in future therapeutic strategies." (PMID 40305202, 2025). "Then, the impact of silencing AQP3 and/or AQP5 in biophysical, biomechanical, and morphological properties of pancreatic cancer cells was investigated by atomic force microscopy (AFM) and two-photon microscopy (TPM)." (PMID 35455986, 2022). "Taken together, our findings demonstrate that the expression of AQP3 and AQP5 promotes alterations of the biological and biomechanical properties of these pancreatic cancer cells." (PMID 35455986, 2022). "In fact, both AQP5 and AQP3 showed measurable peroxiporin activity in pancreatic cancer cells, with AQP5 showing higher efficiency than AQP3." (PMID 31277235, 2019). "Further validation may establish AQP3 and AQP5 as additional prognostic biomarkers for pancreatic cancer, potentially contributing to improving early disease detection, prognosis, and personalized treatment strategies." (PMID 40305202, 2025). "The relative gene expression levels of AQP1, AQP3, AQP5, and AQP9 were analyzed using real-time quantitative PCR (RT-qPCR) in 24 paired pancreatic tumors and adjacent healthy tissues according to variables such as age, gender, and tumor invasiveness and aggressiveness." (PMID 37761834, 2023).
squamous cell carcinoma (14 papers, 2012 to 2025). A carcinoma arising from squamous epithelial cells. "For instance, AQP3-mediated H2O2 uptake was correlated with the activation of the EGFR signaling pathway in human squamous cell carcinoma and lung cancer cell lines, contributing to cancer progression." (PMID 39941100, 2025). "Positive AQP3 staining was seen in 26 Bowen's diseases (2 focal, 24 diffuse), 43 squamous cell carcinomas (3 focal, 7 intermediate, and 33 diffuse), and 19 apocrine carcinomas (3 intermediate, 16 diffuse)." (PMID 34745849, 2021). "High expression of AQP3 in human squamous cell carcinoma and decreased skin tumorigenesis in AQP3 knockout mice has also been reported." (PMID 30555637, 2018). "For example, AQP3 overexpression in AQP3-PC12 cells and epidermoid carcinoma cells (A431), which express high levels of AQP3, accelerates cell cycles, and treatment with the AQP3 inhibitor leads to arrest in the S-G2/M phases and enhances the expression of cyclin D1 and E1 proteins." (PMID 35252273, 2022). "On contrary, Kusayama and colleagues (2011) observed that the immunostaining pattern of AQP3 in human primary squamous cell carcinoma (SCC) was dependent on cancer type since an eminent AQP3 expression was detectable in skin SCC but only a poor expression in lung SCC." (PMID 36233821, 2022). "By immunohistochemistry, diffuse AQP3 expression was seen in all keratotic lesions including seborrheic keratosis, verruca vulgaris, molluscum contagiosum, solar keratosis, Bowen's disease, and squamous cell carcinoma." (PMID 34745849, 2021).
colorectal cancer (13 papers, 2013 to 2025). A primary or metastatic malignant neoplasm that affects the colon or rectum. "Moreover, the expression of AQP3 in resected colorectal cancer samples was associated with lymph node and distant metastasis." (PMID 35847914, 2022). "Recently, this antibody exhibited therapeutic effects in colorectal cancer by suppressing tumor growth, reducing immunosuppressive M2-like tumor-associated macrophages, and maintaining T cell anti-tumor activity within the tumor microenvironment through AQP3 targeting." (PMID 39941100, 2025). "Human EGF (hEGF) can upregulate the expression of AQP3 protein and the migration ability of the human colorectal carcinoma cell line HCT116 in a dose- and time-dependent manner, for which AQP3 expression is partially responsible." (PMID 35847914, 2022). "After the addition of EGF to colorectal cancer cells in vitro, AQP3 expression was observed to be increased." (PMID 32662230, 2020). "AQP8 expression influences migration and invasion of cervical cancer cells, and AQP3 expression enhances pancreatic and colorectal cancer cell invasion and metastasis." (PMID 29922644, 2018). "Specially, AQP1, AQP3 and AQP5 expression has been demonstrated in seven human colon and colorectal cancer cell lines, and they are associated with an early stage of colorectal cancer development." (PMID 27589719, 2016). "For instance, human epidermal growth factor (EGF) upregulates AQP3 expression, thereby enhancing colorectal cancer cell migration via the phosphoinositide 3-kinase (PI3K)/Akt signaling pathway, being also associated with metastasis in colorectal cancer patients." (PMID 39941100, 2025). "AQP1, AQP3, AQP5, and AQP9 are associated with colorectal cancers; among them, it has been indicated that AQP5 promotes the proliferation and metastasis of CRC; moreover, elevated expression of AQP5 in CRC tissue is associated with a poor prognosis of colorectal cancer." (PMID 36114463, 2022). "AQP3 plays a role in tumor differentiation and metastasis along with epidermal growth factor receptors in colorectal cancer, and therefore, these both may be potential targets for inhibition." (PMID 30555637, 2018). "AQP1, AQP3, AQP5, and AQP9 all have roles associated with colorectal cancer." (PMID 30555637, 2018). "Additionally, human epidermal growth factor significantly increased the expression of AQP3 and consequently the migration of human colorectal carcinoma cells (HCT116) in a dose- and time-dependent manner." (PMID 27589719, 2016). "mRNA expression of AQP1, AQP3, and AQP5 was examined in seven colon and colorectal cancer cell lines, and protein expression was confirmed in four of these cell lines." (PMID 35847914, 2022). "Conversely, in human colorectal carcinoma cells HCT116, hEGF upregulates AQP3 expression through PI3K/AKT signaling." (PMID 35874817, 2022). "Within this final set, the largest proportion of studies addressed AQP1, followed by AQP5, AQP4, AQP3 and AQP9, for a diverse array of cancer types, including brain, lung, breast and colorectal cancers." (PMID 32679804, 2020). "AQP1, AQP3, AQP5, AQP8 and AQP9 play a clinically relevant role in hepatic cancer as they do in colorectal cancer." (PMID 30555637, 2018). "In addition, AQP3 and epidermal growth factor receptor (EGFR) are both involved in the differentiation and metastasis of colorectal cancer, thus serving as a potential inhibition target." (PMID 32662230, 2020). "The mechanisms for AQP3-facilitated pancreatic and colorectal cancer cell migration have not yet been determined." (PMID 29922644, 2018).